EP300 (EP300 lysine acetyltransferase)
Diseases named in the same sentence as EP300 in open-access papers (continued):
Sharing a sentence is not in itself a finding about the gene and the disease.
colon adenocarcinoma (4 papers, 2021 to 2023). "We revealed the colon adenocarcinoma patients (COAD) with mutations of a CRs set (EP300, MSH6, NSD2 and TRRAP) mediate a better survival with low expression of MAP2 and could benefit from taxnes." (PMID 36180906, 2022). "Analyzing The Cancer Genome Atlas (TCGA), we found significantly lower CREBBP and EP300 expression in tumors of patients with colon adenocarcinoma (COAD) and rectum adenocarcinoma (READ) compared with matched nonmalignant tissues." (PMID 34258881, 2021).
Huntington disease (4 papers, 2011 to 2020). Huntington disease (HD) is a rare neurodegenerative disorder of the central nervous system characterized by unwanted choreatic movements, behavioral and psychiatric disturbances and dementia. "It was interesting to note that genes involved in Huntington’s disease were enriched in this signature, namely MAP2K7, PDPK1, NCOR2, EP300, and REST." (PMID 27698411, 2016).
meningioma (4 papers, 2012 to 2024). A generally slow growing tumor attached to the dura mater. "Regarding downstream gene cascades of Akt, apoptosis-induced genes including CASP9 (3.78-fold), CDKN1A (8.64-fold), AXIN2 (2.78-fold), APC2 (3.12-fold), and EP300 (5.35-fold) were detected with significant down-regulation in fibroblastic meningiomas." (PMID 23285163, 2012). "After extracting and overlapping the downregulated genes during every stage of meningioma development within three datasets, we identified 497 genes, including well-defined tumor suppressor genes PTEN, PML, EP300, and SMAD4." (PMID 37791390, 2024).
metastatic disease (4 papers, 2016 to 2026). "Most selected CNVs in posttreatment metastatic tumours were also found to be selected in pretreatment metastatic samples, except EP300 amplification, FBXW7 deletion and PTEN deletion." (PMID 36739462, 2023). "Two metastatic tumors (Cases 22 and 23) harbored heterozygous SMARCB1 deletions accompanied by broad 22q losses affecting CHEK2, NF2, and EP300." (PMID 41317331, 2026).
osteoarthritis (4 papers, 2011 to 2025). A noninflammatory degenerative joint disease occurring chiefly in older persons, characterized by degeneration of the articular cartilage, hypertrophy of bone at the margins and changes in the synovial membrane. "EP300 is associated with protein ubiquitination and is up-regulated in trabecular bone samples and osteoblasts from osteoarthritis patients." (PMID 38027135, 2023). "Further analysis of these enriched pathways in injurious hydrostatic pressure highlighted differential expression of several genes known to be involved in osteoarthritis, such as Fgf2, Ep300, Ngf, Adam9, Igfbp3, Sox9, Comp, Col6a1, Col6a2 and Col11a1." (PMID 38144567, 2023). "Not surprisingly, altered EP300 expression has been associated with the Wnt pathway, a key mediator of bone formation as well as cartilage alterations in osteoarthritis." (PMID 21470430, 2011). "In addition, several genes known to play a key role in progression of osteoarthritis (e.g., Fgf2, Ep300, Ngf, Adam9, Igfbp3, Sox9, Comp, Col6a1, Col6a2 and Col11a1) were modulated in our injurious hydrostatic pressure hip cap datasets, thereby validating this approach." (PMID 38144567, 2023). "Subsequently, EP300 binds to the FOXC1 promoter and promotes the enrichment of H3K27Ac at the FOXC1 promoter to elevate FOXC1 expression, ultimately regulating IL‐1β‐induced chondrocyte damage and promoting the progression of osteoarthritis." (PMID 40703976, 2025).
osteoporosis (4 papers, 2016 to 2023). A condition of reduced bone mass, with decreased cortical thickness and a decrease in the number and size of the trabeculae of cancellous bone (but normal chemical composition), resulting in increased fracture incidence. "MiRNA-132-3p was increased in bone tissues of unloading osteoporosis rats and inhibited primary rat osteoblast differentiation by targeting Ep300." (PMID 35435443, 2022). "Besides, miR-132-3p regulated osteoblast differentiation in osteoporosis by targeting EP300 and SIRT1." (PMID 27556448, 2016).
pancreatic adenocarcinoma (4 papers, 2016 to 2025). "The COSMIC gene with the most variation explained by TF coexpression is EP300, with an average of 79% added variance explained from TFs in pancreatic adenocarcinoma (PAAD)." (PMID 40041206, 2025).
small cell lung carcinoma (4 papers, 2006 to 2023). Small cell lung cancer (SCLC) is a highly aggressive malignant neoplasm, accounting for 10-15% of lung cancer cases, characterized byrapid growth, and early metastasis. "Among small-cell lung cancers, frequent mutations are seen in retinoblastoma 1 (RB1), E1A-binding protein p300 (EP300), MLL2, and PIK3CA." (PMID 26970967, 2016).
Stroke (4 papers, 2023 to 2025). Sudden impairment of blood flow to a part of the brain due to occlusion or rupture of an artery to the brain. "The discrimination ability of FOXO4 and Ep300 proteins in determining the presence of stroke was measured in ROC analysis." (PMID 40900757, 2025).
systemic lupus erythematosus (4 papers, 2020 to 2025). An autoimmune multi-organ disease typically associated with vasculopathy and autoantibody production. "In the third trimester, systemic lupus erythematosus and proteasome were enriched in the acute disease while Fc gamma R-mediated phagocytosis (VAV1, MARCKSL1, WASF2, DNM2, HCK, MAP2K1 genes) and adherens junction (ACTG1, WASF2, SMAD4, CSNK2B, EP300 genes) represented the subclinical category." (PMID 32012176, 2020).
adenoma (3 papers, 2016 to 2019). A neoplasm arising from the epithelium. "As expected, we found that APC was the most frequently mutated gene across the adenomas studied, while other WNT pathway genes (CTNNB1, EP300, TCF7L2, and AMER1) were altered less frequently." (PMID 31781186, 2019).
autism spectrum disorder (3 papers, 2015 to 2024). A spectrum of developmental disorders that includes autism, and Asperger syndrome. "Patient E2 with EP300 c.5492_5494del p.(Arg1831del) continued to have recurrent otitis, and autism spectrum disorder was also diagnosed." (PMID 36797748, 2023).
bladder (3 papers, 2025). "We observed a strong negative association between KDM6A‐mut signature score and other aberrations associated with bladder patients with PD‐L1 responders, and a strong positive correlation with CREBBP‐mut and EP300‐mut scores." (PMID 40693457, 2025).
chronic lymphocytic leukemia (3 papers, 2015 to 2025). "PLX51107 binds to the bromodomains of CBP and EP300, inhibiting CpG-induced primary chronic lymphocytic leukemia (CLL) cell proliferation." (PMID 40430531, 2025).
chronic myeloid leukemia (3 papers, 2018 to 2023). "Our results show that the GATA1/MYC axis is as a key component of EP300/CREBBP bromodomain inhibitors mechanism of action in chronic myeloid leukemia (CML) cell line K562." (PMID 29884215, 2018). "EP300 is abundant at super-enhancers and coincident with sites of GATA1 and MYC occupancy in chronic myeloid leukemia (CML) cell line K562." (PMID 36831561, 2023). "For example, CREBBP/EP300 mutations frequently occur in primary and relapsed pediatric ALL, aggressive NK-cell leukemia (ANKL), and chronic-phase chronic myeloid leukemia (CML-CP)." (PMID 36831561, 2023).
gastric adenocarcinoma (3 papers, 2019 to 2025). "In an additional analysis of 55 WES gastric adenocarcinomas from patients treated with anti–PD-1 therapy in the second- or third-line setting, only six cases harbored coding mutations in CREBBP and/or EP300." (PMID 41301688, 2025). "Subgroups with high TMB and MSI scores are significantly enriched for mutant samples in CREBBP and/or EP300, especially in GEJ and gastric adenocarcinomas (>30%) and esophageal adenocarcinomas (16%), compared to TMB-Low and MSS groups (3–4%)." (PMID 41301688, 2025).
histiocytic sarcoma (3 papers, 2011 to 2022). An aggressive malignant neoplasm with a poor response to therapy, usually presenting as stage III/IV disease. "The other three patients exhibit an expansion of clones harbouring del(8p) with additional driver mutations (EP300, MLL2 and EIF2A), with one patient developing trans-differentiation into CD19-negative histiocytic sarcoma." (PMID 27199251, 2016).
lymph node metastasis (3 papers, 2018 to 2020). "EP300 mutation was associated with tumor grade, pathological T stage and lymph node metastasis, predicting a shorter cumulative survival status." (PMID 31632486, 2019). "The univariate analysis showed that EP300 mutant, tumor grade, lymph node metastasis and pathological T were significant risk factors for OS status (HR, 1.668; 95% CI, 1.062-2.621; p = 0.026)." (PMID 31632486, 2019). "High EP300 gene expression was statistically significantly correlated with worse RFS in TNBC and basal-like BC patients with lymph node metastasis or high-grade tumors (G3)." (PMID 33167919, 2020).
Menke-Hennekam syndrome (3 papers, 2024 to 2025). "Menke-Hennekam syndrome (MKHK) is a recently described rare autosomal dominant disorder caused by loss-of-function variants in exon 30 or 31 of CREBBP (CREB-binding protein) or EP300 genes." (PMID 40860344, 2025). "Subsequently, individuals carrying these variants were established as having an entity distinct from RSTS, recently described as Menke-Hennekam syndrome (MKHK1 and MKHK2; OMIM: 618332 and 618333, for variants in CREBBP and EP300, respectively)." (PMID 38553851, 2024). "Menke-Hennekam syndrome consists of at least three domain/region-specific subtypes within the genes CREBBP and EP300 (MKHK-ZZ, MKHK-TAZ2, and MKHK-ID4)." (PMID 38553851, 2024).
non-Hodgkin lymphoma (3 papers, 2015 to 2025). Distinct from Hodgkin lymphoma both morphologically and biologically, non-Hodgkin lymphoma (NHL) is characterized by the absence of Reed-Sternberg cells, can occur at any age, and usually presents as a localized or generalized lymphadenopathy associated with fever and weight loss. "For instance, a recent report shows that a novel miRNA over-expressed in DLBCL (miR-10393-3p) is significantly anti-correlated with the expression of KMT2D and EP300, two genes that are involved in chromatin regulation and that are recurrently mutated in non-Hodgkin lymphoma (NHL)." (PMID 26404381, 2015).
stomach cancer (3 papers, 2017 to 2024). "EP300 has been reported to play a role in tumorigenesis, and inactivating mutations in EP300 have been described in several solid tumor types (e.g. colorectal and gastric tumors)." (PMID 29371938, 2017).
type 1 diabetes (3 papers, 2017 to 2021).
acral melanoma (2 papers, 2022 to 2024). "Here, we report that SOX10 and EP300 are commonly co-amplified in both UV-associated cutaneous and acral melanomas." (PMID 38994683, 2024). "Recent studies have found that EP300 is amplified in acral melanomas at a high frequency." (PMID 38994683, 2024).
angioimmunoblastic T-cell lymphoma (2 papers, 2023 to 2025). A mature T-cell non-Hodgkin lymphoma, characterized by systemic disease and a polymorphous infiltrate involving lymph nodes and extranodal sites. "Mutations in the CREBBP/EP300 gene are also often identified in other types of lymphomas besides DLBCL, including FL, in situ follicular neoplasia, peripheral T-cell lymphoma (PTCL), angioimmunoblastic T-cell lymphoma (AITL), and plasmablastic lymphoma." (PMID 40426926, 2025).
atrial septal defect (2 papers, 2025). Interauricular communication is a congenital malformation characterized by a communication between the atrial chambers of the heart. "Variants in genes associated with atrial septal defects and ventricular septal defects (e.g., DOCK6, EOGT, EP300, EVC, EVC2, and SEMA3C) have also been identified in patients." (PMID 41153298, 2025).
cervical squamous cell carcinoma (2 papers, 2017 to 2025). A squamous cell carcinoma arising from the cervical epithelium. "EP300 overexpression enhanced the protein expression of Ki67 in the tumor tissues of mice injected with cervical squamous cell carcinoma cells." (PMID 40095759, 2025).
chronic kidney disease (2 papers, 2020 to 2021). Impairment of the renal function secondary to chronic kidney damage persisting for three or more months. "Heterozygous germline EP300 mutations were first described in Rubinstein–Taybi syndrome (RBTS), a congenital neurodevelopmental disorder associated with renal development abnormalities and an increased risk of chronic kidney diseases." (PMID 34067022, 2021).
colorectal tumors (2 papers, 2011 to 2019). "The QPIHPNNM peptidedoes have partial homology to the Ep300 protein (QP**PNNM) and an undefined cell adhesionmolecule-related/down-regulated by oncogenes precursor (transmembrane protein,QPIHP), with the lattersuspected to be involved in the development of colorectal tumors." (PMID 21408169, 2011).
COVID-19 (2 papers, 2023). A disease caused by infection with severe acute respiratory syndrome coronavirus 2. "In conclusion, our study provides global insights into the transcriptome profiles of host responses in COVID-19-vaccinated individuals and identifies MAPK1, CDC42, PPP2CA, EP300, YWHAZ and NRAS as hub genes that are significantly correlated with the vaccine response." (PMID 37096063, 2023).
ependymoma (2 papers, 2015 to 2020). A WHO grade II, slow growing tumor of children and young adults, usually located intraventricularly. "Further functional investigation of EP300 and other genes will provide pivotal information on the pathophysiology of ependymomas and potential therapeutic targets." (PMID 25909290, 2015).
familial Alzheimer disease (2 papers, 2011 to 2014). A degenerative disease of the brain that causes gradual loss of memory, judgment, and the ability to function socially. "In addition, the promoted signaling mechanism of EP300 is important in the neuronal survival process and this gene was related to other neuronal disorders, such as familial Alzheimer's disease." (PMID 24959624, 2014).
fungal infection (2 papers, 2007 to 2022).
gallbladder cancer (2 papers, 2021 to 2025). "Firstly, we compared the mRNA expression level of EP300 in the gallbladder cancer tissues and adjacent normal tissues." (PMID 33613109, 2021). "Differentially expressed analysis showed that EP300, a major histone acetyltransferase modifying H3K27ac signal, is highly expressed in gallbladder cancer and correlation analysis illustrated that EP300 is positively related with KIF11 in almost all the cancer types." (PMID 33613109, 2021).
head and neck cancer (2 papers, 2013 to 2017). A primary or metastatic malignant neoplasm affecting the head and neck. "Consistent with a positive role in tumor progression, expression of the short LAMA3 isoforms, which is multiply controlled by the transcriptional co-activator EP300, along with the transcription factors AP-1, CREB1 and USF1, is increased and portends a dismal prognosis in head and neck cancers." (PMID 24324612, 2013).
infertile (2 papers, 2021 to 2024). "We found KIF2C-miRNAs (has-miR-3154, 6075, 6760-5p, 1251-5p, 186-sp)-TFs (EP300, SP1) might work in spermatozoa of infertile men." (PMID 34591790, 2021).
invasive breast carcinoma (2 papers, 2021 to 2023). A carcinoma that infiltrates the breast parenchyma. "In line with its potential role in DCIS, data from publicly available invasive breast carcinoma repositories showed that while high RNA expression of β6 in the bulk tumour was associated with higher levels of EP300, MMP13 expression was also significantly increased in high EP300 expressing patients." (PMID 36864079, 2023).
muscular dystrophy (2 papers, 2018 to 2022). Muscular dystrophy (MD) refers to a group of more than 30 genetic diseases characterized by progressive weakness and degeneration of the skeletal muscles that control movement. "In zebrafish, specific inhibition of cbp/p300 leads to a muscular dystrophy-like phenotype, while ep300 knockdown causes skeletal, cardiac and neural abnormalities modelling defects present in patients." (PMID 36225316, 2022).
myeloid malignancies (2 papers, 2018 to 2025). "While CREBBP/EP300 gene mutations have been described in association with myeloid neoplasms." (PMID 39969535, 2025).
myopia (2 papers, 2018 to 2023). "Interestingly, RTS patients with EP300 mutations were frequently documented with severe myopia phenotype." (PMID 30245926, 2018). "FI network analysis revealed important network modules and regulator linker genes (EP300, CTNNB1) potentially related to high myopia development." (PMID 30245926, 2018).
neuropathic pain (2 papers, 2012 to 2020). Chronic pain caused by damage to nerve fibers. "We manifested that miR-30a-3p might involve the EP300-mediated BDNF activation via targeting the acetylated histone H3 and H4 on BDNF promoter in neuropathic pain." (PMID 33103739, 2020).
oral squamous cell carcinoma (2 papers, 2021 to 2025). "EP300, a histone acetyltransferase, regulates gene expression and has been implicated in oral squamous cell carcinoma progression through TGF‐β/Smad4 signaling." (PMID 41312415, 2025). "Under the condition of oral squamous cell carcinoma, EP300 activated LINC00941 transcription through upregulating H3K27ac modification in its promoter." (PMID 34544413, 2021).
plasmacytoma (2 papers, 2016). Plasmacytoma is a localized mass of neoplastic monoclonal plasma cells that represents approximately 5% of all plasma cell neoplasms. "Noteworthy, CBP/EP300 bromodomain inhibition has been shown to target a more limited subset of hematologic cell lines, with a bias toward MM/plasmacytoma cell lines and enrichment of signatures for pathways important in MM growth and survival." (PMID 27903272, 2016).
prion disease (2 papers, 2022 to 2023). A transmissible disease that is caused by a protein that is able to induce abnormal folding of normal cellular proteins, leading to characteristic spongiform brain changes, which are associated with neuronal loss without an inflammatory response. "Among genes associated with prion diseases, the over-expression of some (PSEN1, FYN, SMC3, CHD2, EP300) in late-cycle could be rationalized by considering related proteins in humans, which, when expressed in their monomeric (soluble) form, exert protective functions for cellular homeostasis." (PMID 37048113, 2023).
sarcopenia (2 papers, 2025). Progressive decline in muscle mass due to aging which results in decreased functional capacity of muscles. "Using the MTA‐MO method, we identified 639 gene targets, and by analysing PPIs and querying public databases, we narrowed this list down to seven potential hub genes associated with sarcopenia (ESR1, ATM, CDC42, EP300, PIK3CA, EGF and PTK2B)." (PMID 40045692, 2025). "Applying MTA-MO to multi-omics data identified seven potential hub genes associated with sarcopenia: ESR1, ATM, CDC42, EP300, PIK3CA, EGF, and PTK2B." (PMID 41303670, 2025).